CDK2 (cyclin dependent kinase 2)
Diseases named in the same sentence as CDK2 in open-access papers (continued):
Sharing a sentence is not in itself a finding about the gene and the disease.
ovarian carcinoma (continued). "The Spearman’s rank correlation analysis showed that the expression of cyclin H is positively correlated with the tumor grade, the FIGO stage, histological grade, and the peritoneal metastasis of ovarian cancer and is also positively correlated with the Ki67 and p-CDK2 in ovarian cancer." (PMID 32694938, 2020). "We then examined whether Cul4B upregulates the expression of CDK2 and CyclinD1 by repressing miR-372 in ovarian cancer." (PMID 32622365, 2020). "Similarly, the expression of cyclin H, MAT1, CDK7, and p-CDK2 also decreased in cyclin H silenced ovarian cancer." (PMID 32694938, 2020). "Our results further show the mechanisms underlying the stimulation of proliferation and stemness of ovarian cancer cells by CD83, involving interaction with MAP3K7 and activation of MAPK signaling pathway, as well as downstream FOXO1/p21/CDK2/Cyclin B1 and STAT3/DKK1 cascades." (PMID 32823589, 2020). "Interestingly, exposure to 10 μM ZEA significantly downregulated the expression of CDK2 genes, which regulate the cell cycle and are involved in ovarian cancer." (PMID 30108608, 2018). "The observation that Cdk2 inhibitor SNS-032 selectively induces apoptosis in ovarian cancer cells with elevated CCNE1 expression prompted us to investigate its efficacy to suppress ovarian tumor progression with the well-established ovarian tumor peritoneal metastatic colonization model." (PMID 26204491, 2015). "Recent study showed that ovarian cancer cells overexpressing CCNE1 exhibited greater Cdk2 activity." (PMID 26204491, 2015). "We thus hypothesized that ovarian cancer cells with elevated CCNE1 expression would be more sensitive to the suppression of Cdk2 activity." (PMID 26204491, 2015). "We initially performed immunoblotting to detect Cdk1 and Cdk2 in ovarian cancer cell lines." (PMID 26204491, 2015). "Despite these differences, the decline in the activity of Cdk2 within 24 h of exposure to MF was a commonality among the 10 cell lines studied, as we have shown in ovarian cancer cells for MF and more recently for two other antiprogestins, ORG-31710 and CDB-2914." (PMID 21619605, 2011). "Abnormal expression of HSP90AA1 and CDK2 could affect the progression of ovarian cancer." (PMID 36483919, 2022). "In this study, RPS6 knockdown resulted in decreased Cyclin E, CDK2, Cyclin D1, CDK4, and CDK6 levels, and reduced Rb phosphorylation, thus hindering the transition from G0G1 to S phase, causing most cells to be blocked in G0G1 phase, thereby inhibiting ovarian cancer cell growth." (PMID 32862831, 2020). "The identification of outliers from functional genomic data also helps to uncover potential indications and predictive biomarkers associated with candidate targets (e.g. ovarian cancer and CCNE1 amplification for CDK2 inhibitors) that may guide the development of precision medicine strategies." (PMID 27296290, 2016). "Furthermore, exposure of OV2008 and SK-OV-3 ovarian cancer cells to a cytostatic concentration of MF increased the abundance of the cell cycle inhibitors p21cip1 and p27kip1, decreased the abundance of Cdk2 and cyclin E, and decreased Cdk2 activity." (PMID 21619605, 2011). "In various cancer cells, including glioblastomas, liver cancer, ovarian cancer, and colorectal cancer cells, CDK20 can activate CDK2 and control the cell cycle progression of cancer cells." (PMID 41302865, 2025). "In A2780 ovarian cancer cells treated with 2‐fluoro‐6‐formylphenylboronic acid, the downregulation of cyclin A‐CDK1/CDK2 and cyclin E‐CDK2 complexes (which manage the S phase) triggered S phase arrest, displaying antiproliferative effects on these cells." (PMID 40682482, 2025).
ovarian carcinoma (continued). "The CDK2/4/6, cyclin D1/E1 and RB1/pRB1 protein expression were investigated in 300 ovarian cancers and correlated with clinicopathological parameters and patient outcomes." (PMID 38612869, 2024). "In the current study, we have comprehensively investigated the sub-cellular localisation and clinicopathological significance of cyclins D1/E1, CDK2/4/6 and RB1/pRB1 in a cohort of clinical ovarian cancers." (PMID 38612869, 2024). "The investigators observed that cyclin E1 (CCNE1) was overexpressed in 30% of established ovarian cancer cell lines, and such cancer cells were 40 times more sensitive to SNS-032 therapy, a CDK2 small molecule inhibitor." (PMID 38612869, 2024). "Several studies revealed, counterintuitively, that CDK2 participates in DNA repair, and CCNE-amplified ovarian carcinomas rely on CDK2 for DNA repair through homologous recombination, its inhibition compromises replication fork repair." (PMID 38279263, 2024). "In ovarian cancer, STC1 stimulated high expression of cell cycle-related proteins (cyclin A/B1/D1 and CDK2/4) for rapid proliferation of tumor cells and mitotic cycle of G1 to S was dramatically shortened." (PMID 38215156, 2024). "Other amplified oncogenes frequently found in epithelial ovarian cancer were ERBB2, STAT3, PIK3C2B, CDK2, and CDK4, as well as SWI/SNF chromatin modification complex genes, including ARID1A and SMARCC1." (PMID 36430324, 2022). "Taken together, our findings suggest that CDK1 and CDK2 regulate the activation of MLK3 and JNK during G1/S and G2/M phases to control ovarian cancer cell division." (PMID 35843311, 2022). "Taken together, our results suggest that phosphorylation of MLK3 by CDK1 and CDK2 is important for the regulation of MLK3 and c-Jun N-terminal kinase activities during G1/S, G2, and M phases in ovarian cancer cell division." (PMID 35843311, 2022). "HSP90AA1 and CDK2 were selected by the analysis of the relationship between SMB and ovarian cancer, and the relationship between the PI3K-Akt signaling pathway and SMB." (PMID 36483919, 2022). "The levels of p-RB, cyclin D1, cyclin E, CDK2, CDK4, or CDK6 by RPS6-KD were reduced in NSCLC cells, ovarian cancer cells, and drug-resistant melanoma cells." (PMID 35008473, 2021). "Consistently, the G0/G1 checkpoint regulators, such as cyclin D1, cyclin E, CDK2, CDK4, CDK6, and p-RB, are diminished by RPS6-KD in ovarian cancer cells." (PMID 35008473, 2021). "Recently, a CDK2 and CDK5 dual-targeting degrader TMX-2172 was identified and showed strong anti-proliferative activity against the ovarian cancer cell line OVCAR by inducing the degradation of CDK2." (PMID 34488823, 2021). "In this study, we found that CD83 associated with MAP3K7 and activated MAPK cascades to further regulate FOXO1/p21/CDK2/CCNB1 and STAT3/DKK1 signaling pathways, thus activating proliferation and spheroid formation of ovarian cancer cells." (PMID 32823589, 2020). "In ovarian cancer, CUL4B was overtly up-regulated in cancer tissues and CUL4B facilitated cancer cell proliferation by mediating CDK2 and CyclinD1." (PMID 33292255, 2020). "Using real-time PCR, we found that silencing SMYD3 significantly decreased the mRNA levels of CCNA2, CCNB2, CCND2, CDK1 and CDK2 (p<0.05) but increased the mRNA levels of WEE1 (p<0.05), suggesting an essential role for SMYD3 in ovarian carcinoma proliferation." (PMID 31417652, 2019). "We have directly compared the response and resistance mechanisms for CDK4/6 inhibition (PD0332991) and CDK2 inhibition (SNS032; dinaciclib) in a panel of ovarian cancer cell lines." (PMID 25557169, 2015). "Using ovarian cancer as a model system, we have compared directly the acute effect of selective CDK4/6 inhibition (PD0332991 = palbociclib) or CDK2 inhibition (SNS032, dinaciclib), as well as mechanisms of resistance." (PMID 25557169, 2015).
ovarian carcinoma (continued). "It has been reported that RU486 induces G1-S blockage of the cell cycle in human ovarian cancer cells and that RU486 reduces the activity of cdk2, enzyme that is involved in the regulation of the transcription factor E2F1 which modulates S-phase progression." (PMID 24982875, 2014). "In addition, overexpression of CDK2 was found in only 6% of EOC patients, but its level of expression was positively correlated with CCNE abundance, suggesting that overexpression of both CDK2 and CCNE is significantly associated with development of malignant ovarian tumors." (PMID 23236518, 2012). "To address this hypothesis, we have comprehensively evaluated the clinicopathological significance of the CDK2, CDK4, CDK6, cyclin D1, cyclin E1, RB1 and pRB1(Ser 795) protein expression in a clinical cohort of epithelial ovarian cancer." (PMID 38612869, 2024). "In ovarian cancer, where SHP-1 expression levels are high, inhibiting SHP-1 expression gradually reduces tumor growth by increasing the intracellular levels of Cdk2/p27 Kip1 and Cdk2/SHP-1 complex, which is opposite to the mechanism used by SHP-1 to inhibit cell division." (PMID 38203502, 2023). "We chose the ovarian cancer cell line OVCAR-3, where prior work has established via in vitro and in vivo genetic knockdown experiments that growth of OVCAR-3 cells is driven by cyclin E1 overexpression and dependent on CDK2." (PMID 37270540, 2023). "Protoapigenone exhibits a substantial cytotoxic potential on human ovarian cancer cells by inhibition of SKOV-3 and MDAH-2774 cells at the G2/M and S phases of the cell cycle by lowering the expression of p-cyclin B1, cyclin B1, p-Cdk2, and Cdk2 and boosting the inactive p-Cdc25C expressions." (PMID 36386196, 2022). "We propose a model in which CDK1 and CDK2 phosphorylate MLK3, and this phosphorylation works as a “on/off” switch that in turn regulates MLK3 and JNK activity to control cell cycle progression in ovarian cancer cells." (PMID 35843311, 2022). "Moreover, CD83 functions through the activation of MAP3K7-MEK1/2-ERK1/2 cascades to further regulate downstream FOXO1/p21/CDK2/CCNB1 and STAT3/DKK1 signaling pathways, thus activating proliferation and spheroid formation of ovarian cancer cells, respectively." (PMID 32823589, 2020). "We identify the activated TAK1-MEK1/2-ERK1/2 signaling, increased CDK2/cyclin B1 expression, and reduced FOXO1/p21 levels in CD83-overexpressed ovarian cancer cells, indicating that MAPK-ERK1/2-FOXO1 axis is involved in the activation of ovarian cancer cell proliferation by CD83." (PMID 32823589, 2020). "CDK2 is classified as “common essential” by CRISPR analysis but RNAi analysis classifies it as “strongly selective” (this selectivity pertains to ovarian cancer, not shown)." (PMID 31382571, 2019). "In this study, we show that ovarian cancer cell lines with elevated CCNE1 expression are at least 40 times more sensitive to Cdk2 inhibitor SNS-032 than lines without inherent CCNE1 overexpression, non-cancerous OECs and FTSECs." (PMID 26204491, 2015). "Ovarian cancer cells with elevated CCNE1 expression were 40 times more sensitive to Cdk2 inhibitorSNS-032 than those without inherent CCNE1 overexpression." (PMID 26204491, 2015). "Since activated RTK and PI3K signaling was a common motif in CDK2 inhibitor-resistant ovarian cancer cells, we next tested the hypothesis that constitutively active RTK signaling could confer resistance to CDK2 inhibition." (PMID 25557169, 2015). "This uncovers a 40-fold difference in the sensitivity to Cdk2 inhibitor between ovarian cancer cell lines with and without CCNE1 overexpression (P = 0.003)." (PMID 26204491, 2015).
ovarian carcinoma (continued). "Cyclin-dependent kinases (CDK2, CDK4, CDK6), cyclin D1, cyclin E1 and phosphorylated retinoblastoma (pRB1) are key regulators of the G1/S cell cycle checkpoint and may influence platinum response in ovarian cancers." (PMID 38612869, 2024). "HSP90AA1, CDK2, and PIK3CG might be potential targets of SMB in inhibiting ovarian cancer." (PMID 36483919, 2022). "Based on the results of the DTB of SKOV3 cells and the differences in JNK activity in late G1/S, early G2, and M phases, we hypothesized that CDK2 (during early G2 phase) and CDK1 (during early M phase) plays an essential role in regulating MLK3 and JNK activity in ovarian cancer cells." (PMID 35843311, 2022). "In addition, the PI3K-Akt signaling pathway might be the main pathway for SMB to inhibit ovarian cancer because the significant genes HSP90AA1, CDK2, and PIK3CG in this pathway receive the action of multiple ingredients in SMB." (PMID 36483919, 2022). "Consequently, CDK2 inhibition sensitizes cyclin E1-driven but not RAS-driven ovarian cancer cells to platinum-based chemotherapy." (PMID 25557169, 2015). "Interestingly, compared with parental cells, ovarian cancer cells resistant to flavopiridol and cisplatin showed the increased expressions of CDK1, cyclin D3 and Rb, decreased expressions of cyclin B, and equal expressions of cyclin A, cyclin E, CDK2, CDK4." (PMID 25962959, 2015). "To determine the effect of Cdk2 inhibitor on ovarian cancer cell growth, we showed that ovarian cancer cells with elevated CCNE1 expression are at least 40 times more sensitive to Cdk2 inhibitor SNS-032 than those without CCNE1 overexpression, immortalized OECs and FTSECs." (PMID 26204491, 2015). "Thus, whereas ovarian cancer cell lines can be clearly segregated into PD0332991-sensitive and resistant lines, IC50 values for current CDK2 inhibitors show a continuum within a narrow dose range that may be the result of non-cell cycle CDKs affected by SNS032 (CDK9) and dinaciclib (CDK5, 9)." (PMID 25557169, 2015). "Unlike SKOV3, TOV112D, and HEY ovarian cancer cells, T80 and T29 normal ovarian epithelial cells did not exhibit decreased levels of p-CDK1, p-CDK2, or p-Rb when treated with URMC099." (PMID 35843311, 2022).
prostate carcinoma (74 papers, 2005 to 2026). A carcinoma that arises from epithelial cells of the prostate gland. "CDK2 is a key regulator of cell cycle progression, and its dysregulation has been implicated in prostate cancer development and progression." (PMID 41595499, 2026). "Hydroxytyrosol has also previously caused cell cycle arrest in prostate cancer cells by inhibiting cyclin-D1/E and CDK2/4 and inducing inhibitory p21/p27." (PMID 30004416, 2018). "Other investigators have also reported an association between histone H3 and H4 acetylation, cdk2 reduction and diminished growth in bladder and prostate cancer cells." (PMID 24935000, 2014). "Everolimus resistance has also been associated with a considerable increase in cdk2 in prostate cancer and in RCC cells." (PMID 24935000, 2014). "In giant cell carcinoma and prostate carcinoma cells, berberine also decreased G0/G1 phase-associated cyclins (D1, D2, E, Cdk2, Cdk4, and Cdk6), inducing G0/G1 arrest and suppressing cell proliferation." (PMID 23213296, 2012). "Previously, we detected that treatment of prostate cancer cells with DBF causes CDK2 activation." (PMID 34564151, 2021). "CDK2 plays a pivotal role in the development and progression of breast and prostate cancer through its ability to phosphorylate androgen, estrogen, and progesterone receptors." (PMID 39800748, 2025). "Olomoucine and NU2058, which are selective CDK2 inhibitors, were shown to be synergistic with antiandrogens in prostate cancer cells, providing further evidence for this as a possible therapeutic approach." (PMID 40075623, 2025). "The absence of AR activity has been shown to lead to reduced levels of cyclin D3 and cyclin A, reduced CDK4 and CDK2 activity, the hypophosphorylation of Rb, and G1 arrest in prostate cancer cells." (PMID 40075623, 2025). "MYBL2 is currently not druggable, so using a MYBL2 gene signature, we identified CDK2 as a potential therapeutic target for phenotypic plastic prostate cancer." (PMID 39113611, 2024). "For example, CDK2(ranked 16th in patient TCGA-BH-A18M) was recently discovered to be essential for the proliferation of prostate cancer cell." (PMID 38254011, 2024). "Herein we found that MA inhibits prostate cancer cell proliferation by decreasing CDK2, CDK4, and CDK6 expression and concurrently increasing p27, Rb, p-Rb expression." (PMID 39624845, 2024). "Together, these data indicate that CDK2 inhibition represents a novel therapeutic approach to treat prostate cancers progressing on AR signaling inhibition and exhibiting phenotypic plasticity that includes increased expression and function of MYBL2." (PMID 39113611, 2024). "The role of CA treatment on proliferative proteins (Cyclin-D1, CDK-2, Cyclin-D2) expression in prostate cancer cells PC-3 was examined by western blotting." (PMID 39574470, 2024). "Our study identifies MYBL2 as a MR-TF in phenotypic plastic prostate cancer and implicates CDK2 inhibition as a novel therapeutic target for this most lethal subtype of prostate cancer." (PMID 39113611, 2024). "Of most interest to us, due to potential novelty for treating phenotypic plastic prostate cancer, were the cell cycle–related CDKs, which included CDK2, CDK5, and CDK7." (PMID 39113611, 2024). "Other recent results have indicated that Jun D knockdown can reduce the protein levels of cell cycle regulators including c-Myc, CDK4, and CDK2 in prostate cancer cells." (PMID 33669811, 2021). "It has been shown in prostate cancer that miR-1296 can decrease the expression of CDK2 by acting as a potential therapeutic target." (PMID 34284793, 2021). "In contrast, the protein levels of c-Myc, CDK4, and CDK2 were increased by overexpression of Jun D in prostate cancer cells." (PMID 33669811, 2021). "Inhibition of CDK2 reduces invasion of prostate cancer cells and reintroduction of CDK2 rescues the invasion ability, indicating that CDK2 is a crucial factor in metastasis of cancer." (PMID 33665162, 2020).